CD4 (CD4 molecule)
Diseases named in the same sentence as CD4 in open-access papers (continued):
Sharing a sentence is not in itself a finding about the gene and the disease.
AIDS (continued). "We showed that young people at greatest risk of experiencing a new AIDS event or death following transfer to adult care were those who had an AIDS diagnosis in paediatric care, or who had a lower CD4 count at their last paediatric care visit." (PMID 33939876, 2021). "TCM can increase the CD4+ T-cell count among patients with HIV/AIDS who have a baseline CD4+ T-cell count of <350 cells/mL." (PMID 34326884, 2021). "Other significant associations with viral suppression were related to the study period, timing of ART initiation and the severity of HIV disease (lower CD4 cell count, higher viral load and clinical AIDS)." (PMID 34006927, 2021). "While there was a consensus that ART should be started as soon as possible in patients with clinical AIDS, a CD4 cell count threshold for ART initiation has been debated since the introduction of modern ART in 1996." (PMID 34006927, 2021). "With the emergence of monoclonal antibodies and flow cytometry, it was possible to clarify the role of CD4+ T cells in HIV-AIDS." (PMID 33996838, 2021). "To this end, we defined an absolute CD4+ T cell count of < 350 cells/μL, initiation of long-term antiretroviral therapy, or progression to AIDS and death as the endpoints." (PMID 34804062, 2021). "A low CD4/CD8 ratio accurately describes an immune dysfunction and has been used as a biomarker for disease progression of several non-AIDS-associated pathologies, such as kidney disease, heart disease, neurocognitive disorders." (PMID 34556049, 2021). "A viral load of <500 copies/mL along with a CD4 count of >750 in an adult patient means that there is only a 3.6% chance that the patient will progress to AIDS in a nine-year time frame." (PMID 34094761, 2021). "To address these issues, we developed a HLA-mismatched allogeneic adoptive immune therapy (AAIT) combined with ART regimen specifically tailored for severely immunosuppressed AIDS patients with CD4+ T-cell counts <50 cells/μl." (PMID 33958574, 2021). "Past AIDS defining illnesses, treatment interruptions, low CD4 count at diagnosis and having multiple prior ART regimens were still significantly associated with VNS in both genders in univariable analysis." (PMID 34706742, 2021). "Subjects in the PI group were more frequently injecting drug users, had a lower nadir CD4+ T‐cell count, had more frequently been diagnosed with AIDS, and had higher rates of virological failure during follow‐up." (PMID 34036745, 2021). "Depletion of CD4+T cells in vivo can simulate the effect of severe immune compromise, characteristic of AIDS in murine TB models." (PMID 34134725, 2021). "A decrease in CD4 counts to significantly low levels below 200 cells/μl is a sign of progression to AIDS in HIV-infected individuals." (PMID 34214127, 2021). "Similar to findings in the asymptomatic group, the circulating CD4+ concentration was inversely related to the salivary TTV titer in the group with AIDS-KS (p < 0.0001, Spearman rank correlation test)." (PMID 35096897, 2021). "The CD4+ T-cell count of the patients with HIV/AIDS increased from a baseline mean of 352 (SD, 209) to a mean of 476 (SD, 204) over the fourteen years of follow-up." (PMID 34326884, 2021). "We recommend initiating TCM therapy as early as possible in patients with HIV/AIDS who have a CD4+ T-cell count of <350 cells/mL." (PMID 34326884, 2021). "Out of 550 samples, 17 (3.1%) of them were found to have CD4+ T cell count less than 100 cells\mm3, which is considered as one of the important parameters to define the AIDS stage of infection." (PMID 34508432, 2021). "Currently, systemic chronic immune activation is considered as the driving force of CD4+ T-cell depletion and acquired immunodeficiency syndrome (AIDS)." (PMID 33820568, 2021). "The apoptosis of uninfected bystander T cells is crucial in AIDS pathogenesis, and is responsible for the fast and massive depletion of CD4+ T cells leading to immunodeficiency." (PMID 34233649, 2021).
AIDS (continued). "There were 79% and 68% decreases in AIDS-related mortality risk in immediate ART and delayed ART compared with late ART in both high and low CD4+ cell count groups." (PMID 34592916, 2021). "The median salivary TTV titer and circulating HIV titer were higher, and the CD4+ count was lower, in individuals positive for AIDS-KS than in the asymptomatic subjects (p < 0.0001)." (PMID 35096897, 2021). "CD4+ T-cell depletion is pathognomonic for AIDS in both HIV and simian immunodeficiency virus (SIV) infections." (PMID 34367156, 2021). "In this review, adult HIV/AIDS patients whose CD4 count was less than 200 were five times more likely to get depressed than those with their CD4 count greater than 200 (AOR = 5.1; 95% CI: 2.89, 8.99)." (PMID 34721902, 2021). "The 47 subjects with AIDS-KS were younger than the asymptomatic individuals (38.2 vs. 44.8 years, p < 0.0001), had a lower median log10 CD4+ level (127 vs. 559 mm3, p < 0.0001) and a higher circulating median log10 HIV titer/ml (2.4 vs. <1.0, p < 0.0001)." (PMID 35096897, 2021). "Immunologic non-response is commonly defined by a failure to restore normal CD4+ T cell counts in blood despite virus suppression on ART, and INR individuals are at a particularly high risk of serious non-AIDS co-morbidities and mortality." (PMID 34881278, 2021). "The increase of CD4 cell count reduces the incidence of various AIDS and non AIDS defining conditions." (PMID 33526074, 2021). "Poorer HRQoL scores are closely correlated with worse clinical health measures such as low CD4 T-cell count and the occurrence of AIDS-defining events." (PMID 34272399, 2021). "Another study also found that patients with HIV/AIDS who had a CD4+ T-cell count of >500 cells/mL at the time of treatment initiation kept their CD4+ T-cell count at >500 cells/mL over the seven years after initiating treatment." (PMID 34326884, 2021). "A case report of a 35-year-old man with acquired immunodeficiency syndrome (AIDS) (CD4 lymphocyte count of 30 cells/μl) was diagnosed with GAE on biopsy after MRI imaging showed multiple ring-enhancing lesions with hemorrhages." (PMID 33833918, 2021). "There is little available data on the long-term trends in CD4+ T-cell counts among patients with HIV/AIDS receiving TCM therapy." (PMID 34326884, 2021). "The influence of TCM on the CD4+ T-cell count of patients with HIV/AIDS is related to the CD4+ T-cell level at the time of initial treatment." (PMID 34326884, 2021). "Whilst HIV productively replicates in activated CD4 T cells, contributing to their depletion and progression to AIDS, latent infection is established in resting memory CD4 T cells and can result in the development of HIV viral reservoirs." (PMID 33872331, 2021). "A study that used samples from the European Multicenter AIDS Cohort Study (MACS), found an association between FcγRIIa-131R/R genotype and a faster rate of CD4+ T cell decline and disease progression compared to individuals with the R131H or H131H genotypes." (PMID 34017334, 2021). "At the time of diagnosis, 233 (36%) patients were at the AIDS stage as defined by the World health organization clinical staging classification and 351 (54%) had a CD4 count < 200 cells/mm3 (median CD4/mm3: 169, IQR:48–348)." (PMID 33430783, 2021). "We enrolled 650 newly HIV-diagnosed patients (median age: 35, women: 55%, heterosexuals: 81%, diagnosed with AIDS or CD4 < 200 cells/mm3: 63%)." (PMID 33430783, 2021). "An annual questionnaire was sent to 383 HIV/AIDS referral hospitals across Japan to collect information (CD4+ lymphocyte count, time of onset, outcome, and antiretroviral therapy [ART] status) of patients diagnosed with any of 23 ADIs between 1995 and 2017." (PMID 34411193, 2021). "Patients who presented with ADCs as their initial symptoms of HIV/AIDS were often at advanced stage of HIV infection, characterized as low CD4 levels, suggesting long-term underlying HIV infection rather than recent infection." (PMID 34934097, 2021).
AIDS (continued). "When CD4+ T cell counts decline below the limit of 200 cells/μl of blood, cell-mediated immunity is severely compromised, resulting in AIDS, a fatal complication characterized by life-threatening opportunistic infections and cancers." (PMID 34456931, 2021). "Two patients were passed away as follows: a 54-year-old HIV patient was found to be in the advanced stage of AIDS, with CD4 count of only 8 cells/μl and the CSF pressure measured was over 350mmH2O at admission." (PMID 34051748, 2021). "Those HIV/AIDS patients with CD4 count of >350 were 0.77 times less risky (p = 0.000) at any given time than those patient with CD4 count of <200." (PMID 34972122, 2021). "Patients with higher baseline CD4+ cell counts had a lower cumulative incidence of AIDS-related death." (PMID 34592916, 2021). "When a patient’s CD4+ cell count reaches more than 350/mm3 and the viral load reaches undetectable levels within the first year of starting treatment, AIDS patients are predicted to have a normal life expectancy." (PMID 34794501, 2021). "For instance, the rate of KS in acquired immunodeficiency syndrome (AIDS) patients is inversely proportional to the CD4 count." (PMID 33620515, 2021). "Compared to women, men were more likely to be diagnosed with an AIDS-defining event (45% versus 29%, p < 0.0001) and a lower CD4 count (median CD4/mm3: 131 versus 200, p < 0.0001)." (PMID 33430783, 2021). "At enrolment, median age was 35.2 years (1st-3rd quartile: 28.9, 42.9), median CD4 count was 397 cells/μL, 1,961 (13.2%) individuals had an AIDS diagnosis and 5,102 (34.3%) had a viral load ≥100,000 copies/mL." (PMID 33882093, 2021). "Patients infected via blood transmission had higher plasma HIV loads and lower CD4+ cell counts than patients infected by sexual transmission, resulting in faster progression of AIDS or earlier death." (PMID 34592916, 2021). "We therefore sought to explore the impact of ART initiation time on AIDS-related mortality in patients with high and low CD4+ cell counts." (PMID 34592916, 2021). "For patients with HIV/AIDS who had a baseline CD4+ T-cell count of 200–350 cells/mL, older patients reached a CD4+ T-cell count of approximately 350 cells/mL at a faster rate compared with younger patients in the TCM + cART group." (PMID 34326884, 2021). "In the present study, long sleepers more frequently had a history of AIDS-defining events, a lower CD4 nadir and a CD4+/CD8+ ratio < 1 (a surrogate marker of immune activation and inflammation), markers of more severe disease." (PMID 33429860, 2021). "The results show that the effect of TCM on the CD4+ T-cell counts of patients with HIV/AIDS is related to the CD4+ T-cell level at the time of initial treatment." (PMID 34326884, 2021). "Among HIV+ individuals, factors related to HIV including positive AIDS status, lower nadir CD4, current ART treatment, and a longer duration of HIV infection were statistically significantly associated with a higher likelihood of balance disturbances." (PMID 33536072, 2021). "There was a trend for earlier initiation of ART among older patients, those with more severe HIV-disease (lower CD4 cell count, clinical AIDS, higher viral load)." (PMID 34006927, 2021). "Most of HIV-infected patients experience a rapid decline in CD4 counts and accelerated development of AIDS." (PMID 34804062, 2021). "Although absolute CD4+ T-cell count was initially used prognostically to assess progression to AIDS, it was observed that the rate of CD4+ T-cell decline varied significantly." (PMID 34122382, 2021). "HIV-infected individuals are characterized by continuous HIV RNA replication and CD4+ T cell count decline, and most of them progress to AIDS in an average of 10 years." (PMID 34082709, 2021). "AIDS patients have very low level of circulating CD4+ T cells, while in our animal model, TCRβ−/− mice completely lack all the T cells." (PMID 34899731, 2021).
AIDS (continued). "In the present study, we used these medical data to analyze the annual trends in CD4+ T-cell counts to evaluate the curative effect of TCM on the treatment of patients with HIV/AIDS who were also receiving cART therapy." (PMID 34326884, 2021). "From the Retroviridae family, the human immunodeficiency virus (HIV) primarily infects CD4+ cells, escalating to acquired immunodeficiency syndrome (AIDS), and can bypass the BBB from systemic circulation." (PMID 34357070, 2021). "HIV-infected patients have the CD4/CD8 ratio usually diminished in most patients, and it is related to higher inflammation, activation, immune deregulation, and increased risk of non-AIDS morbidity and mortality." (PMID 34497613, 2021). "PCNSL usually occurs in patients with advanced immunosuppressed status and low CD4+ lymphocyte counts (<50 cells/μL), and frequently with an AIDS-defining illness before lymphoma diagnosis." (PMID 34771697, 2021). "These macaques showed very low CD4+ T cell counts (<100 cells/μl) during the observation period and showed AIDS symptoms at 402–1225 days after the challenge." (PMID 34686680, 2021). "HIV-1 infection increased the abundance of anellovirus, with AIDS patients (CD4 < 200) showing the highest abundance." (PMID 33952659, 2021). "The World Health Organization (WHO) defines Acquired Immune Deficiency Syndrome (AIDS) in people living with HIV (PLWH) either clinically (presence of stage 4 AIDS-defining illness) or immunologically (CD4 cell count less than 200 per mm3)." (PMID 34941669, 2021). "The more frequent NADEs driving to mortality with previous AIDS or <200 CD4/μL are malignancies, cardiovascular and end-stage liver disease." (PMID 33670229, 2021). "Regarding the characteristics of the HIV patients, their median CD4 count was 164 cel/mm3; lymphoma diagnosis was an AIDS defining event for 41% of them, who were recently diagnosed and not on antiretroviral therapy at the moment of the TST." (PMID 34059022, 2021). "The final stage of AIDS occurs when the CD4+ cell count drops below 200 cells/mm or when opportunistic infections develop." (PMID 34595076, 2021). "But in the French study, one third of patients were very immunosuppressed (AIDS with less than 50 CD4/mm3) and a vast majority of them died before bacteriological diagnosis." (PMID 34702233, 2021). "Studies have shown that there is a significant correlation between the recovery of CD4+ T cells and malnutrition in AIDS patients with poor immune reconstitution after ART." (PMID 35003070, 2021). "Patients with AIDS and severely depressed CD4 counts have significantly compromised cell-mediated immunity." (PMID 34888109, 2021). "We found a strong association between ART outcome and the baseline CD4 count and pretreatment clinical stage of HIV/AIDS." (PMID 33684169, 2021). "AIDS represents the final stage of HIV disease when patients display clinical manifestations including low CD4+ T cell counts and compromised cellular immunity that renders increased susceptibility to infection and tumor formation." (PMID 34804062, 2021). "Regardless of the CT regimen or ART combination, the TTV was inversely proportional to the CD4+ count in 40 patients with AIDS-KS receiving CT (Description of characteristics of AIDS-KS subjects)." (PMID 35096897, 2021). "Study have shown that HIV-infected individuals with normal CD4+ T cell counts tend to develop to the stage of AIDS more quickly if their CD38 expression levels are higher." (PMID 33820568, 2021). "Applying the RITA algorithm, nine patients were reclassified from recent to established HIV-infection based on AIDS-defining illness (n = 1), CD4 count (n = 4), or viral load (n = 4)." (PMID 36304001, 2021). "The model demonstrates many characteristics observed clinically of AIDS, e.g., the reduction of CD4+ T-cells, and the low levels and long latency time of the free virus in a human host body." (PMID 33806939, 2021).
AIDS (continued). "Our results indicated that the burden of liver cirrhosis was 1.4% among cART-naive AIDS patients, and was distributed in older age and different categories of CD4 levels." (PMID 33351812, 2020). "HIV and SIV infections in humans and macaques (MAC), respectively, induce a chronic state of immune activation, which is the driving force behind CD4 + T cell depletion and AIDS." (PMID 33298174, 2020). "This method can make full use of all the available data, including HIV and AIDS diagnoses as well as CD4+ T-cell counts at diagnosis." (PMID 31964392, 2020). "Antiretroviral therapy (ART) rapidly suppresses HIV replication, and the number of CD4+ T cell counts recovers, preventing AIDS." (PMID 33384690, 2020). "Of these 11 studies, 4 (36%) excluded PLWH with any history of an AIDS-defining condition (except malignant neoplasm and CD4 cell count)." (PMID 33258905, 2020). "The majority of older patients (n = 32, 65.3%) presented with a CD4 count less than 200 cells/dl, or an AIDS defining illness compared to their younger counterparts (n = 43, 30.9%), which was a statistically significant finding (p < 0.0001)." (PMID 33129258, 2020). "At the time of this study, universal ART was not available in the DR; instead, ART initiation was based on CD4 cell count and other AIDS-defining criteria." (PMID 33119663, 2020). "They modelled the changing relationship between HIV viral load and CD4 cell counts in AIDS studies during the course of treatment." (PMID 32336264, 2020). "Six out of these seven patients had AIDS, with a CD4 cell count less than 150 cells/μl at the time of diagnosis." (PMID 33235807, 2020). "As reported by researchers in the past, AIDS patients with low baseline CD4+ T-cell counts were more likely to develop new OIs than others." (PMID 32727383, 2020). "AHD was defined as an initial CD4 count <200 cells/μL or an AIDS‐defining event within one month of HIV diagnosis." (PMID 33225623, 2020). "A significant number of individuals start HIV/AIDS care at later stage of infection (later presenters) and usually present low T CD4 counts even with complete viral suppression." (PMID 32286360, 2020). "HIV infection status and most recent available CD4+ count were ascertained through direct provider report or the Enhanced HIV/AIDS Reporting System,* a CDC application that assists health departments with reporting, data management, and analysis." (PMID 32673295, 2020). "Joint modeling of longitudinal biomarkers and time-to-event data for analyzing AIDS clinical trials using CD4 count measurement as an important predictor of survival will result in unbiased and more efficient estimates." (PMID 32953683, 2020). "In untreated persons with HIV (PWH), viral replication and antigen exposure contribute to sustained immune activation which, in turn, is found to be an independent predictor of CD4+ T-cell depletion and progression to AIDS." (PMID 33117394, 2020). "Cytomegalovirus retinochoroiditis (CMV-R) primarily affects patients with AIDS exhibiting CD4 cell counts < 50 cells/mm3." (PMID 33122781, 2020). "Human immunodeficiency virus type 1 (HIV-1) infection of CD4+ T cells in the gut plays an insidious role in acquired immunodeficiency syndrome (AIDS) pathogenesis." (PMID 33193273, 2020). "HIV/AIDS not only induces depletion of CD4 T-cells but also reduces CD8 T-cells leading to downmodulation, reduction in T-cell subpopulation and defective cell mediated immunity against any microbial infection." (PMID 33175844, 2020). "This multiforce separation is continuous and its efficiency was up to 92% for cells expressing the HIV/AIDS relevant epitope (CD4)." (PMID 32899657, 2020). "While the implied mean CD4 at diagnosis over time – based on the fit to new diagnoses and AIDS deaths – appears plausible, actual data should be incorporated in the future when available." (PMID 32590964, 2020). "36% had a CD4 count greater than 500 cells/mm3, 28% had a CD4 count between 200 and 500 cells/mm3, and 36% had AIDS." (PMID 32181043, 2020).